SNORD116 (Small nucleolar RNA SNORD116 )
Synonyms: LOC124903255
Gene: Small nucleolar RNA gene on chromosome 13 (39,857,135 to 39,857,227, reverse strand). Ensembl gene ENSG00000212553.
Gene Ontology:
Biological process: RNA processing
Cellular component: nucleolus
Homologues: Orthologues: chimpanzee SNORD116 (98% identical), macaque SNORD116 (92% identical), guinea pig SNORD116 (73% identical), guinea pig SNORD116 (72% identical), guinea pig SNORD116 (71% identical), guinea pig SNORD116 (70% identical), guinea pig SNORD116 (69% identical), guinea pig SNORD116 (62% identical), guinea pig SNORD116 (54% identical). Paralogues in human: SNORD116-3 (80% identical), SNORD116-9 (80% identical), SNORD116-4 (78% identical), SNORD116-5 (78% identical), SNORD116-7 (78% identical), SNORD116-1 (77% identical), SNORD116-2 (77% identical), SNORD116-8 (77% identical), SNORD116-6 (76% identical), SNORD116-14 (74% identical), SNORD116-17 (73% identical), SNORD116-19 (73% identical), and 20 more.
Diseases named in the same sentence as SNORD116 in open-access papers:
SNORD116 is named in the same sentence as 32 diseases in open-access papers, as found by Europe PMC text mining. Sharing a sentence is not in itself a finding about the gene and the disease. The quoted sentences say what the papers report.
Obesity (8 papers, 2016 to 2025). Accumulation of substantial excess body fat. "Adult-onset deletion of Snord116 in the mediobasal hypothalamus results in hyperphagia, with a subset of mice further developing obesity and increased fat mass." (PMID 29376887, 2018). "The presence of hyperphagia, concomitant with obesity in a subset of mice, after Snord116 deletion in the mediobasal hypothalamus of adults indicates that Snord116 plays a role in the hypothalamic control of appetite and food intake." (PMID 29376887, 2018). "In addition, a subset of mice in which Snord116 expression is reduced in part of the adult hypothalamus show hyperphagia and obesity." (PMID 40048253, 2025). "Moreover, Snord116 +/− mice exhibit cognitive dysfunction and the deletion of Snord116 in the mediobasal hypothalamus of adult mice leads to a hyperphagic phenotype, with some animals developing obesity." (PMID 39407757, 2024). "Furthermore, in animal models of PWS, knockout Snord116 mice displayed cognitive deficits, growth retardation, hyperphagia, and marked obesity." (PMID 34504512, 2021). "They report that such neurons, with deletions encompassing Snord116, show reduced expression of PCSK1 (encoding prohormone covertase), which has been previously implicated in human obesity, and a transcription factor NHLH2, which regulates expression of the PCSK1 gene." (PMID 29376887, 2018). "Importantly, loss of Snord116 is not accompanied by any signs of obesity and, paradoxically, Snord116-deficient mice appear even protected from high fat-diet induced obesity." (PMID 33016258, 2020). "In conclusion, we report that adult deletion of Snord116 in the mediobasal hypothalamus represents a hyperphagic murine model of PWS, with a subset of mice further developing obesity concomitant with increased fat mass." (PMID 29376887, 2018). "PWS animal models, such as Magel2- and Snord116-null mice fed with a standard chow diet did not develop the delayed-onset obesity described in PWS." (PMID 36007929, 2022). "Congenital paternal Snord116 deletion (Snord116+/–P) mice have impaired growth, but do not develop hyperphagia or obesity." (PMID 29376887, 2018). "Snord116+/–P mice thus remain small without transitioning to developing obesity." (PMID 29376887, 2018). "However, the second phase of classical PWS development – the establishment of an obese phenotype in later life – is absent and Snord116−/− mice are actually resistant to HFD-induced obesity." (PMID 26726071, 2016). "Taken together, the overactive feeding behaviour seen in Snord116−/− mice, albeit without an associated development of obesity, is similar to the hyperphagic phenotype observed in humans with PWS, supporting a role for Snord116 in the early development of the PWS phenotype." (PMID 26726071, 2016).
Prader-Willi syndrome (7 papers, 2014 to 2026). "While there is evidence to consider the altered expression of SNORD115 and SNORD116, a primary cause of Prader-Willi syndrome, most recently those two and some other snoRNAs, has been implicated in the pathogenesis of schizophrenia." (PMID 31888770, 2019). "AS and Prader-Willi syndrome (PWS) are imprinted neurodevelopmental disorders that are often caused by large deletions of human chromosome 15q11–q13 over the Snord116 gene locus, but the deletion differs in its parent-of-origin." (PMID 25233079, 2014). "Prader-Willi syndrome (PWS) is a rare imprinting-related neurodevelopmental disorder caused by loss of paternally expressed genes within the chromosome 15q11-q13 region, including SNORD116, MAGEL2, and NDN." (PMID 41677631, 2026).
autism (3 papers, 2020 to 2025). Persistent deficits in social interaction and communication and interaction as well as a markedly restricted repertoire of activity and interest as well as repetitive patterns of behavior. "Research has also shown that another snoRNA, the snoRD116, is critically implicated in the pathogenesis of Prader-Willi, which is a genetic syndrome with autism-like symptomatology." (PMID 40868063, 2025). "The reported findings suggested the presence of novel interactions between expression of UBE3A and SNORD116, with brain specific processes underlying motor and language impairments in autism and these chromosome 15 imprinted genetic disorders." (PMID 36980949, 2023). "The findings suggest presence of novel interactions between expression of UBE3A and SNORD116 in PBMCs and brain specific processes underlying motor and language impairments and autism features in these disorders." (PMID 33116122, 2020).
schizophrenia (3 papers, 2018 to 2025). A major psychotic disorder characterized by abnormalities in the perception or expression of reality. "It is significant that the RNA-Seq study that showed changes in SNORD115 and SNORD116 expression in females with schizophrenia also showed changes in the levels of the snoRNA U2, a component of the spliceosome that removes intronic sequences from precursor-mRNA in females with schizophrenia." (PMID 29657307, 2018). "To date, the way SNORD115 and SNORD116 mediate their effect in schizophrenia is not clear." (PMID 29657307, 2018).
ameloblastoma (2 papers, 2017 to 2021). The most common odontogenic tumor, arising from the epithelial component of the embryonic tooth and usually affecting the molar-ramus region of the mandible or maxilla. "The result corroborates that SNORA65, SNORA21, SNORA47, SNORD116-25 and LINC340, which were validated here by RT and qPCR assays, belonged to the top most significantly expressed snoRNAs and lncRNAs in ameloblastoma." (PMID 27965463, 2017). "Small nucleolar RNAs (snoRNAs) comprise a particular group of noncoding RNAs, which role in odontogenic tumors is still unknown, although the overexpression of SNORD116-25, SNORA11, SNORA21, SNORA47 was previously demonstrated in ameloblastomas." (PMID 33680332, 2021).
Anxiety (2 papers, 2016 to 2025). Intense feelings of nervousness, tension, or panic often arise in response to interpersonal stresses. "The Magel2 and Snord116 knockouts had increased anxiety, and the Ndn-deficient mice showed improved spatial learning and memory as well as skin-scraping—a behavior commonly observed in PWS patients." (PMID 27857842, 2016). "We first assessed activity in an open field to determine whether Snord116 deletions result in changes in the locomotor response to a novel environment or demonstrate general anxiety." (PMID 40869911, 2025).
Growth Deficiency (2 papers, 2008 to 2023). "One study found that a deletion of the Snord116 cluster lead to growth deficiency and hyperphagia in mice; another study suggested that the same cluster may be involved in the regulation of epigenic factor expression that is important for circadian rhythm." (PMID 37107593, 2023).
Infertility (2 papers, 2009 to 2025). "Further, failure to thrive associated with loss of the snoRNA HBII-85 could contribute to later infertility in PWS, although fertility was reportedly normal in two independent strains of mice deficient for the murine ortholog MBII-85/Snord116." (PMID 19172181, 2009). "Mice exhibit lower expression of Snord116 outside the brain, for instance in gonadal tissue, which may explain why Snord116 KO mice do not exhibit infertility as PWS patients do." (PMID 40101781, 2025). "Importantly, Snord116 KO mouse models failed to recapitulate key phenotypes of PWS such as obesity and infertility." (PMID 40101781, 2025).
psychosis (2 papers, 2021 to 2025). "Taken together, the results demonstrated here show that Snord116 deletion can recapitulate several of the behavioral phenotypes associated with animal model or human presentations of psychosis." (PMID 40869911, 2025). "It is plausible that the loss of Snord116 function may alter the expression of many of these genes in ways that can result in differential presentations of psychosis in the human PWS population." (PMID 40869911, 2025). "Our results indicate that a Snord116 deletion in mice results in psychosis-like behavior and is sufficient to increase c-Fos expression in the anterior cingulate cortex and hippocampus, suggesting regional neuronal hyperactivity." (PMID 40869911, 2025). "Snord116 deletion also results in behavioral phenotypes consistent with psychosis, most notably in stressful paradigms, with deficits in sensorimotor gating and augmented contextual as well as cued fear conditioning." (PMID 40869911, 2025). "Taken together, these data suggest that Snord116 deletion recapitulates many similar features found in psychosis mouse models and provides additional detail on the genetic underpinnings of psychosis." (PMID 40869911, 2025). "In this study, we sought to assess basal activity in the ACC and hippocampal subfields in mice with the paternal deletion of Snord116 and assess psychosis-like behaviors in several domains, including motor and affective behaviors, learning and memory behaviors, and sensorimotor gating." (PMID 40869911, 2025). "We hypothesize that Snord116 deletion will recapitulate the behaviors of relevant psychosis mouse models, and that brain regional hyperactivity will be present in these Snord116 deletion mice." (PMID 40869911, 2025). "By using a comprehensive behavioral battery, we can determine the specific features of psychosis affected by Snord116 deletion, which could contribute to a psychiatric presentation." (PMID 40869911, 2025). "Furthermore, it is unknown if brain regional phenotypes associated with psychosis, such as hyperactivity of the anterior cingulate cortex (ACC) and hippocampus, are present in paternal Snord116 deletion mice." (PMID 40869911, 2025). "As the Snord116p−/m+ mice have only a microdeletion of a single paternally inherited gene within the region, this raises interesting questions about the unique role of Snord116 in the expression of psychosis and could potentially be used as a distinct target for both PWS and psychosis treatments." (PMID 40869911, 2025).
endometriosis (1 paper, 2016). The growth of functional endometrial tissue in anatomic sites outside the uterine body. "Among the selected genes, SNORD116, RPLP2, RPL38 and 40S ribosomal protein S28 (RPS28) were most elevated ones in endometriosis patients, which was consistent with our in vitro experimental findings using miR196a2-C vector." (PMID 27741504, 2016).
hypogonadism (1 paper, 2021). A disorder characterized by decreased function of the gonads. "MKRN3, NDN, and SNORD116, genes that are located in the PWS critical region, have been associated with GnRH secretion and hypothalamic dysfunction leading to hypogonadism." (PMID 34640379, 2021).
lung carcinoma (1 paper, 2025). "If SNORD116 is a negative regulator of PI3K signalling, this may account for the apparent downregulation of SNORD116 in some forms of cancer such as AML and lung cancer." (PMID 40101781, 2025).
melanoma (1 paper, 2017). A malignant, usually aggressive tumor composed of atypical, neoplastic melanocytes. "Of particular interest, the result revealed that LINC340, LINC342 and SNORD116-25 have been correlated to neuroblastoma, melanoma, small cell lung cancer, and bone marrow cells of multiple myeloma." (PMID 27965463, 2017). "It was observed that aberrantly expressed LINC340 and SNORD116-25 have been found in melanoma, neuroblastoma, and multiple myeloma bone marrow cells." (PMID 27965463, 2017).
cancer (2 papers, 2018 to 2025). A tumor composed of atypical neoplastic, often pleomorphic cells that invade other tissues. "However, SNORD116 has also been implicated in other diseases including cancer, cardiovascular disease and osteoarthritis." (PMID 40101781, 2025). "Interestingly, some of the targets such as Malat1, Meg3 and Rny3 are associated with cancer and therefore may relate to the role of SNORD116 in cell turnover and/or oncogenesis." (PMID 40101781, 2025). "SNORD116 is also dysregulated in multiple forms of cancer, potentiating a role in cancer proliferation and survival." (PMID 40101781, 2025).
tumor (2 papers, 2017 to 2023). "It was found that the accumulated ncRNA levels (LINC340, LINC342, SNORD116-25, SNORA11, SNORA21, SNORA47, SNORA65; r = 0.5789, p-value = 0.0075) had a positive but moderate correlation with tumour size." (PMID 27965463, 2017).
SNORD116 also shares sentences with these, for which no sentence is quoted: leukemia (2 papers); Angelman syndrome (1); cervical carcinoma (1); cognitive deficits (1); Failure to thrive (1); genetic disorder (1); Hyperphagia (1); Intellectual disability (1); liver cancer (1); morbid obesity (1); motor neuron diseases (1); multiple myeloma (1); neuroblastoma (1); neurodevelopmental disorder (1); odontogenic tumors (1); ovarian carcinoma (1); small cell lung carcinoma (1).